TNF (tumor necrosis factor)
Diseases named in the same sentence as TNF in open-access papers (continued):
Sharing a sentence is not in itself a finding about the gene and the disease.
diabetes (continued). "Importantly, the increase in TNF levels is related with the development and progression of renal disease in patients with diabetes." (PMID 32046074, 2020). "Immediately after diabetes manifestation, antibody combination therapies were initiated over 5 days with anti-TNF-α (tumour necrosis factor), anti-IL-1β (interleukin), or anti-IFN-γ (interferon) together with anti-TCR for the reversal of the diabetic metabolic state in the IDDM rat." (PMID 32607871, 2020). "Another research suggested that luteolin could ameliorate the cognitive dysfunctions in STZ-induced diabetic rat model by downexpression of glycation end products (AGEs), inhibition of IL-1 and TNF- and upregulating the expressions of GAP-43 and SYN." (PMID 33292335, 2020). "Studies have shown that miR-146 expression in peripheral blood monocytes decreased significantly while TRAF-6 mRNA expression increased in patients with type 2 diabetes mellitus and miR-146 expression is negatively linked to TRAF-6 and NF-κB mRNA levels as well as circulating TNF-α and IL-6." (PMID 32337281, 2020). "The increase in IL-6 and TNF-α observed in diabetes state also acts as antierythropoietic factors expressed in the present study by the decrease in erythrocytes count, hematocrit, and mean corpuscular of haemoglobin values, which are some conventional signs of anemia." (PMID 33293987, 2020). "Multiple-antioxidant therapy prevented higher expression of tumor necrosis factor alpha (TNF-α), interferon gamma (IFN-γ), and ROS-producing enzymes in a type 1 diabetes mellitus (T1DM) model, clearly supporting an association of oxidative stress, inflammation, and diabetic complications." (PMID 32408480, 2020). "Thus, platelet-derived CAPN1 contributes to the initiation of the sterile vascular inflammation associated with diabetes via the cleavage of PAR-1 and the release of TNF-α from the endothelial cell surface." (PMID 33258989, 2020). "To further unveil the regenerative potential of PIAA under pathophysiological conditions, we treated INS-1 832/13 cells with a cytokine mix containing IL-1β, IFN-γ, and TNF-α, which are released by inflammatory immune cells and contribute to increased β-cell apoptosis during diabetes progression." (PMID 33168920, 2020). "TNF-α and C-reactive protein levels are higher in patients with chronic pancreatitis and type 2 diabetes mellitus than those with isolated chronic pancreatitis, characterizing the persistence of chronic systemic inflammation in case of the combined clinical course of these diseases." (PMID 33456608, 2020). "Hyperglycemia induced circulating mitochondrial DNA change in parallel with increased circulating interleukin-4 and TNF-α in patients with DR, suggesting that mitochondrial DNA change in early diabetes may be an indicator of inflammation and progression of DR." (PMID 33013692, 2020). "We hypothesized that patients using TNFi would have a greater reduction in HbA1c than patients initiating methotrexate based on the pathophysiologic role of TNF in diabetes." (PMID 32905192, 2020). "Interestingly, the effects of total saponins from various natural sources, showed to ameliorate diabetes through inhibiting pro-inflammatory responses showed by reduced TNF-α levels." (PMID 32694996, 2020). "Prospective randomised clinical trials are needed to evaluate the effects of IL-6R inhibition on glycaemic indices, insulin sensitivity and pancreatic β cell function in patients with comorbid RA and diabetes and determine the clinical relevance of differences in IL-6R, IL-1β and TNF inhibition." (PMID 32907617, 2020). "Interestingly, restriction of dietary AGEs resulted in significant decrease in serum levels of MDA and TNF-α, reflecting a close relation between oxidative stress and inflammation in diabetes mellitus." (PMID 32426041, 2020).
diabetes (continued). "In addition, reports have shown that in metabolic disorders such as hyperglycemia and hyperinsulinemia, which are closely related to diabetes, there is an enhanced production of TNF-α from monocytes and macrophages in an in vitro model." (PMID 32148647, 2020). "Changes in the TNF-α system in diabetes can be explained from two points." (PMID 33072216, 2020). "Furthermore, in a mouse model of diabetes, the treatment with mangiferin reduced IL-6, TNF-α, and Il-1β expression by inhibiting PTEN/PI3K/Akt pathway." (PMID 32471207, 2020). "Due to the fact that there are relatively few data on other inflammatory factors in the included original studies, our study only analyzed CRP, TNF-α, and IL-6; other inflammatory factors that affect and participate in the course of diabetes should be explored in future research." (PMID 33456672, 2020). "Monocyte hyperactivity may be reversed in patients with diabetes mellitus by scaling and root planing resulting in reduced monocyte-derived TNFα, high sensitive CRP and sE-selectin." (PMID 32486269, 2020). "Quercetin treated normal rats also showed higher IL-6 and TNF-α levels compared to diabetic rats, implying that quercetin may play an effective role in regulating metabolism in diabetes." (PMID 32694996, 2020). "The presence of Porphyromonas gingivalis in the periodontal pockets affects the glycemic index in diabetes, and the periodontitis-inducing cytokines TNF-α, IL-6 and IL-1β are also insulin antagonists, triggering irreversible changes in the body's immune response and inflammatory state." (PMID 32634783, 2020). "Moreover, the level of TNF-α were significantly reduced in STZ induced diabetes treated groups with valsartan (85.74 ± 3.85 pg/ml; P < 0.01 vs. DC group) and LCZ696 (77.52 ± 5.5 pg/ml; P < 0.001 vs. DC group)." (PMID 32596035, 2020). "However, animal study suggests that HIF-1α still regulates IL-6 expression in diabetic retina as increased HIF-1α, IL-6, and TNF-α are found in diabetic retina of diabetic rats, which can be decreased by the HIF-1α inhibitor." (PMID 33013692, 2020). "Likewise, BRB breakdown was prevented in TNF-α knockout rats after six months of STZ induced diabetes implying that TNFα plays an important role in BRB disruption." (PMID 33240260, 2020). "Also, some of these biomarkers like hs-CRP, IL-6, and TNF-α have direct value on diabetes incidence prediction." (PMID 31901246, 2020). "Studies have demonstrated that activation of neutrophils and macrophage results to oxidative stress as well as inflammatory cytokines release including IL-1β, IL-6 and TNF-α, leading to the decrease of insulin secretion, hepatic steatosis and a series of metabolic disorders in diabetes." (PMID 32028957, 2020). "STZ-induced diabetes increased cardiac oxidative stress such as the elevated isoprostane amount and the depressed plasma SOD activity associated with the increased TNFα expression and the decreased NO amount, whereas myocardial IR further enhanced these oxidative stresses." (PMID 32751309, 2020). "Additionally, Citicoline is known to exert it pro-survival action in diabetic retina by preventing glial activation and suppressing the expression of NF-κB and TNF-α." (PMID 32470946, 2020). "TNF-α has a role in regulating apoptosis and inflammatory processes in diabetes and hepatic injury." (PMID 30937278, 2019). "Moreover, diabetes mellitus leads to increased expression of proinflammatory cytokines, such as TNF-α and IL-1β, and increased inflammation is also considered to be involved in the pathogenesis of depressive symptoms in type 2 diabetes mellitus." (PMID 31681052, 2019). "To assess whether CPT improves inflammatory responses in diabetes-induced hepatic inflammation, we assessed IL-6, IL-1β, and TNF-α amounts in serum." (PMID 31404259, 2019). "However, the gender-dependent regulation of Ca2+ signaling in diabetes and its relationship with TNFα signaling are still unclear." (PMID 30792662, 2019).
diabetes (continued). "TNF-α and IL-1β were increased in the liver of GDM offspring, whereas IL-10, an anti-inflammatory cytokine, was decreased in GDM offspring, indicating an increased risk of developing diabetes." (PMID 31340612, 2019). "Additionally, in other chronic diseases like diabetes mellitus, delayed bone healing correlated with elevated levels of TNF-α, RANKL and high osteoclast activity." (PMID 31831031, 2019). "Studies using the inflammatory cytokines interleukin-6 (IL-6) C-reactive protein, and tumor-necrosing-factor alfa (TNF-α) have shown that regardless of the presence of diabetes these markers are associated with the occurrence of microalbuminuria and mortality." (PMID 30997790, 2019). "With other nbDMARDs as the reference, the incidence rate of diabetes was lowest for patients using hydroxychloroquine (incidence rate ratio 0.42 [95% CI 0.12, 1.44]) and TNF inhibitors (incidence rate ratio 0.47 [95% CI 0.21, 1.07]), but these ratios included the null." (PMID 30673733, 2019). "A natural extract from Centella asiatica, rich in ascorbic acid, asiatic acid, oleanolic acid, stevioside, stigmasterol and α-humulene protects diabetes tissues from stress via antioxidant and anti-inflammatory mechanisms eliciting brain reduced levels of malondialdehyde, TNF-α, IFN-γ, IL-4 or IL10." (PMID 31126031, 2019). "TNF-α can block insulin signal transduction in skeletal muscle by JUN amino terminal kinase (JNK), eventually affect glycometabolism, which is associated with the incidence of diabetes." (PMID 31341840, 2019). "The increase in heart size during pre-diabetes may be attributed to compensatory hyperinsulinemia and augmented TNFα which transform insulin growth factor-1(IGF-1) and lead to hyperplasia of cardiomyocytes." (PMID 30669379, 2019). "Moreover, it has been reported that α-LA ameliorated hepatic steatosis in rats of diabetes fed with high fat by increasing antioxidant defense systems through Nrf2 and consequently decreasing oxidative stress and hepatic TNF-α." (PMID 31635029, 2019). "In contrast, the HFD model is an obese model of diabetes, characterized by the accumulation of triglycerides in the adipose tissue and by activation of macrophages and TNF-α in the adipose tissue and liver, although with less impact in the liver than carrageenan." (PMID 31179345, 2019). "In a study conducted in US administrative claims data, TNF inhibitors and hydroxychloroquine were associated with a reduced risk of diabetes when compared to other non-biologic DMARDs (nbDMARDs)." (PMID 30673733, 2019). "There was a significantly opposite trend in TNF-α, IL-1β, and IL-10 between the n-3 Adq-GDM group and n-3 Def-GDM group, which could lead to differential diabetes risk." (PMID 31340612, 2019). "Plasma aldosterone levels—augmented in diabetic and hypertension patients and experimental models of diabetes—contribute to the increased expression of inflammatory markers, such as TNF-α, chemotactic protein macrophage, transforming growth factor-beta and IL-1β." (PMID 31817997, 2019). "These include HIV, diabetes mellitus, cancer, solid organ transplantation, renal disease tumor necrosis factor alpha (TNF-α) antagonist treatment, alcohol abuse, tobacco use, air pollution, malignancies and an aging population." (PMID 29755957, 2018). "Taken together, we considered that diabetes might increase the level of TNF-α and IL-6 and trigger the degradation of tight junction and the disruption of BBB in the brain, which eventually caused cognitive impairment." (PMID 29867440, 2018). "Treatment with fenoldopam attenuates serum TNF levels in endotoxemic mice with diabetes." (PMID 29780390, 2018). "Increased glycation is known to inhibit IL-10 and TNFα production by immune cells, which suggests that the lower cytokine production may be a consequence of diabetes-mediated intrinsic defect in these cells." (PMID 29996768, 2018). "In rodent diabetes models, the increase in IL-6 and TNFα is maintained up to 24 weeks of age." (PMID 29301251, 2018).
diabetes (continued). "Since it was identified that TNF-α secretion by adipocytes played a role in the body's update of glucose and response to insulin which contributes to the development of diabetes, extensive research has been done looking at the role of inflammation in diabetes." (PMID 30534081, 2018). "These could be useful in patients with TNF-mediated neurodegeneration or as a correctional therapy in diabetes patients." (PMID 29751683, 2018). "In addition, our data confirmed that the pain behavior coincided with the expression changes of inflammatory cytokines (TNF-α, IL-1β, IL-6, and IL-10) in rats with diabetes induced by STZ." (PMID 29713362, 2018). "TNF may even reduce β-cell function by direct effects, further contributing to its role in the development of diabetes." (PMID 29310643, 2018). "Furthermore, we found that bosentan prevents the upregulation of TNF-α induced by diabetes in retinal vessels." (PMID 30428543, 2018). "In the same study, significant correlations of overhydration with markers of nutritional and inflammatory status (lower serum albumin and higher interleukin-6 and tumor necrosis factor-α) were reported in addition to those with systolic blood pressure, cardiovascular diseases, and diabetes mellitus." (PMID 30894885, 2018). "In addition, netrin-1-treated diabetic mice presented a substantial reduction in macrophage infiltration in pancreatic islets and a decrease in circulating TNF-α levels, showing the anti-inflammatory action of netrin-1 in diabetes." (PMID 30532735, 2018). "In summary, we found that treatment with IFX, a TNF-α antagonist, could attenuate alveolar bone loss, osteoclast formation, and RANKL-positive osteocytes in STZ-induced diabetes rats with periodontitis." (PMID 29240821, 2017). "Furthermore, there was increased expression of NF-κBp65, a transcription factor and serum TNF-α and IL-6 levels in diabetes + IR group as compared to diabetic control group (P < 0.001)." (PMID 28181586, 2017). "However, a cohort study reported that melioidosis patients with a preadmission diagnosis of diabetes treated with glibenclamide had decreased levels of TNF-α, IL-18-R1, and IL-8 and lower in-hospital mortality compared to patients without diabetes." (PMID 28740332, 2017). "Moreover, all the metabolic indicators including TC, TG, FFA, GLU, insulin, HOMAIR, HOMAIS, leptin, HbA1C, HDL, LDL, and TNF were previously proved to have the relationship with chronic disease of hypertension, diabetes mellitus, and cardiovascular disease." (PMID 28115972, 2017). "In summary, treatment of mouse models of diabetes with IL-1β- and TNF-antagonists, and with sodium salicylate improved insulin secretion and glycaemia to comparable levels, with an additive effect on insulin secretion with the combination of IL-1β- and TNFα-antagonists." (PMID 28740254, 2017). "Recombinant human (rh) TNF-α also blocks development of diabetes in NOD mice and BB rats." (PMID 28824543, 2017). "When comparing the periodontal status and cytokine levels, TNF-α was correlated with PI for deciduous teeth (Pearson correlation, r=0.935, p=0.002) and with GI for deciduous teeth (Pearson correlation, r=0.772, p=0.042) in patients with diabetes." (PMID 28403363, 2017). "It has been observed that subjects with diabetes treated with a low AGEs diet for 6 weeks exhibit a significant reduction of serum AGEs levels and markers of inflammation as hsCRP, and TNFα, thus reinforcing the role of AGEs in promoting sub-clinical inflammation." (PMID 28426788, 2017). "Therefore, EGCG-induced increment in TNF-α content observed in presence of diabetes can augment oxidative stress and inflammation." (PMID 28098182, 2017). "TNF-α and IL-10 blood levels increased because of diabetes and periodontal disease (p < 0.05)." (PMID 28906456, 2017).
diabetes (continued). "Therefore, the aim of this study is to investigate the effect of maternal diabetes on adipocytokines (adiponectin, leptin and TNF-α) production in F1 offspring in rats, as a potential mechanism for the transgenerational effect of maternal diabetes." (PMID 28078101, 2017). "For instance, peroxisome proliferator-activated receptor-γ (PPAR-γ) activators: conjugated linoleic acid (CLA) and troglitazone inhibit free radical generation and TNF-α and IL-2 and, thus, inhibit the occurrence of diabetes in the Zucker diabetic fatty fa/fa rat." (PMID 28824543, 2017). "Diabetes significantly induced IL-1β and TNF-α expression of the Kupffer cells in STZ-DM mice." (PMID 28493939, 2017). "In another study, L. reuteri could produce molecules that had potential anti-TNF-α activity in vitro and antimicrobial compounds in diabetes." (PMID 28943876, 2017). "Finally, depression itself can directly increase diabetes risk, for instance by triggering the disruption in the regulation of pro-inflammatory cytokines, such as TNF-alpha, whose presence is high in patients with diabetes." (PMID 28759599, 2017). "Cancer tumors exhibit an inflammatory response via increases in cytokines such as nuclear factor kappa beta (NF-κB) and tumor necrosis factor alpha (TNFα); as do situations in cardiovascular disease, diabetes, and hypertension with reactive species being possible initiators." (PMID 28085082, 2017). "A previous study demonstrated that both inflammation and oxidative stress are involved in the process of I/R injury in an experimental model of diabetes and increased pro-inflammatory cytokines including TNF-α and IL-6 were observed at early stages in transient global ischemia." (PMID 26982373, 2016). "TNF-α is the most important pro-inflammatory factor in diabetes." (PMID 26861982, 2016). "Pro-inflammatory cytokines, TNF-α and IL-6, are produced during the inflammatory process and are principal stimulators of acute-phase proteins and other markers of chronic inflammation commonly detected in diabetes mellitus." (PMID 26888412, 2016). "TNF-α has a role in regulating a wide range of physiological events, including apoptosis and inflammatory processes, as well as its role in other diseases such as diabetes." (PMID 27473536, 2016). "Discontinuation brought stability to the treatment of diabetes andthe introduction of a new anti-TNF-α (infliximab) did not cause thesame problem." (PMID 28099601, 2016). "Other stimuli such as TNFα have been shown to alter circadian rhythms and chronic inflammation, such as observed in cardiovascular disease and diabetes may also play a significant role." (PMID 27168152, 2016). "We demonstrated that increased levels of pro-inflammatory cytokines, IL-1β and TNF-α were secreted by BM-derived DC and splenocytes derived from diabetic mice, indicating that diabetes may lead to aberrant activation of BM and splenic derived immune cells." (PMID 26760976, 2016). "In addition, the reduction of antioxidants and elevation of ROS in diabetes mellitus lead to stimulation of TNF-α and ADAM-17 production." (PMID 27579151, 2016). "Indeed, previous studies suggested that the diabetes was an inflammatory disease, which was mainly based on the increased plasma concentrations of IL-6, IL-1, and TNF-α." (PMID 26944557, 2016). "Previous studies have reported that various inflammation markers, e.g., interleukin-6, tumor necrosis factor α (TNFα) and CRP are associated with diabetes It is believed that TNFα contributes to diabetes through its interaction with insulin signaling pathways and beta-cell function." (PMID 26891449, 2016). "Consequently, chrysin prevents the development of diabetes through anti-inflammatory effects, specifically targeting the TNF-α pathway." (PMID 27527213, 2016). "Since human granulocytes secrete TNFα, this could be a possible link between leukocyte count and diabetes." (PMID 26891449, 2016).